MIS18BP1 (MIS18 binding protein 1)
Description:
Required for recruitment of CENPA to centromeres and normal chromosome segregation during mitosis.
Synonyms: C14orf106; KIAA1903; KNL2; M18BP1; FLJ11186; HSA242977
Tractability: PROTAC: UniProt records ubiquitination sites on it; ubiquitination databases record sites on it.
Gene: Protein-coding gene on chromosome 14 (45,203,190 to 45,253,542, reverse strand). Ensembl gene ENSG00000129534.
Subcellular location: Nucleus; Chromosome, centromere
Subcellular location (Human Protein Atlas): Nucleoli; Cytosol
Pathways (Reactome):
Cell Cycle: Cyclin A/B1/B2 associated events during G2/M transition; Deposition of new CENPA-containing nucleosomes at the centromere
Gene Ontology:
Molecular function: protein binding
Biological process: CENP-A containing chromatin assembly
Cellular component: CENP-A recruiting complex; nucleus; chromosome, centromeric region; nucleoplasm
Genetic constraint (gnomAD): Loss-of-function variants: 63 observed, 97.49 expected, observed/expected ratio (o/e) 0.65, 90% interval 0.53 to 0.8. The upper end of that interval is the gene's LOEUF score, 0.8, which puts it in group 3 of 6, group 1 being the genes least tolerant of losing a copy. Missense variants: 1,259 observed, 1,242.7 expected, observed/expected ratio (o/e) 1.01, 90% interval 0.97 to 1.06. Synonymous variants: 353 observed, 414.7 expected, observed/expected ratio (o/e) 0.85, 90% interval 0.78 to 0.93.
Homologues: Orthologues: chimpanzee MIS18BP1 (99% identical), macaque MIS18BP1 (94% identical), dog MIS18BP1 (73% identical), rabbit MIS18BP1 (72% identical), pig MIS18BP1 (68% identical), guinea pig MIS18BP1 (63% identical), rat Mis18bp1 (51% identical), mouse Mis18bp1 (50% identical), tropical clawed frog mis18bp1 (26% identical), zebrafish mis18bp1 (19% identical), Caenorhabditis elegans knl-2 (10% identical).
Diseases named in the same sentence as MIS18BP1 in open-access papers:
MIS18BP1 is named in the same sentence as 12 diseases in open-access papers, as found by Europe PMC text mining. Sharing a sentence is not in itself a finding about the gene and the disease. The quoted sentences say what the papers report.
autism (1 paper, 2023). Persistent deficits in social interaction and communication and interaction as well as a markedly restricted repertoire of activity and interest as well as repetitive patterns of behavior. "Among these putative ETV1 targets are CSF2RB, which has been associated with major depression and schizophrenia, and MIS18BP1, a gene implicated in the autism spectrum." (PMID 36449109, 2023).
prostate carcinoma (1 paper, 2022). A carcinoma that arises from epithelial cells of the prostate gland. "The HPA database suggested that C18orf25, DYNC1LI2, SYNJ1, MAPK1, and ARID4B are highly expressed in normal tissues, and CLOCK, SETD2, ZNF654, XIAP, MIS18BP1, and MBTPS2 are highly expressed in prostate cancer tissues." (PMID 36249009, 2022).
tumor (2 papers, 2013 to 2022). "Mipol1, Foxa1, and Mis18bp1 are three genes associated with cell growth and tumor development." (PMID 23463770, 2013). "In the 20 pairs of clinical samples we collected, rt-PCR results showed that ZNF678, ARID1A, XIAP, MIS18BP1, and MBTPS2 were highly expressed in tumor tissues." (PMID 36249009, 2022).
cancer (1 paper, 2026). A tumor composed of atypical neoplastic, often pleomorphic cells that invade other tissues. "Cancer and reproductive disease add prominent non-MHC signals at TERT and CLPTM1L alongside pan-category genes such as MIS18BP1 and BIRC3." (PMID 41166152, 2026).
MIS18BP1 also shares sentences with these, for which no sentence is quoted: colorectal cancer (1 paper); Fanconi anemia (1); genetic disorders (1); glioblastoma (1); immune diseases (1); major depression (1); reproductive disease (1); schizophrenia (1).